VHL (von Hippel-Lindau tumor suppressor)
Diseases named in the same sentence as VHL in open-access papers (continued):
Sharing a sentence is not in itself a finding about the gene and the disease.
cancer (continued). "Previous studies showed that the growth of VHL−/− ccRCC cancer cells in 2D cultures was independent of HIF-2α activity." (PMID 38979373, 2025). "Degrader activity profiling in relevant cancer cells supportedthe discovery of ACBI4, a PROTAC which forms a highly stable and cooperativeternary complex between VHL and GTP-bound KRAS and which potentlydegrades KRASG12R, leading to antiproliferative effectin KRAS mutant-driven cancer cells." (PMID 41166656, 2025). "This patient is a 32-year-old Chinese female with VHL but no previous history of cancer who underwent WB-MRI in 2018 which showed a 1-cm lesion in the left kidney." (PMID 40138602, 2025). "HIF1A stabilization can thus provide opportunities for early intervention in neoplastic VHL clones, and the VHL-HIF1A axis may be relevant for the development of resistance to the emerging class of PROTAC-based cancer therapies." (PMID 41420106, 2025). "Except for the canonical VHL-mediated rapid proteasomal degradation under normoxia, numerous novel regulators of HIF-1α are being identified, particularly in the context of cancer." (PMID 40164945, 2025). "Considering the multiple cancers VHL is involved in, however, we do not exclude the utility of these other databases in future expansions of this work." (PMID 37883464, 2024). "For six genes [ELP1, GPR161, VHL and SDHA/B/C], a clear lack of mutational constraint calls the pediatric penetrance and/or severity of associated cancers into question." (PMID 38424437, 2024). "Lack of VHL factor function is also central in CCRCCs in general, but the cancers not being a part of inherent VHL disease manifest themselves a few decades later." (PMID 38660133, 2024). "By exploiting the fact that VHL is poorly expressed in platelets, DT-2216, a VHL-based heterobifunctional degrader, exhibits substantial BCL-XL degradation in cancer cells while having minimal effect on platelets, rescuing the compound from on-target and dose-limiting toxicity." (PMID 38165043, 2024). "Under hypoxic conditions or in the absence of VHL, HIF is stabilized and HIF target genes, which are frequently associated with cancer, such as TGF‐α, are overexpressed." (PMID 38320757, 2024). "The first PCR2-targeting PROTAC was composed of a target protein-binding ligand (EED) and an E3 ubiquitin ligase ligand (VHL) and could degrades PCR2 in cancer cells and inhibit cell proliferation in PRC2-dependent cancer cells." (PMID 36770884, 2023). "AXL is a receptor tyrosine kinase expressed in different cancer cell types, and the gene expression is regulated by HIF1α and HIF2α in hypoxic cancer cells lacking VHL protein." (PMID 37190141, 2023). "Although VHL-defective cancers can be targeted with clinical success by inhibiting its downstream effector HIF1a or VEGF-driven angiogenesis, we hypothesize that VHL function could be restored, at least in part, through ASO-mediated transcript modification." (PMID 37834310, 2023). "Compared to VHL, XIAP, and AHR, which were highly expressed in less than half of cancer types in TCGA, PHF14 may serve as a good candidate for pan-cancer usage over co-opted E3 ligases in terms of expression pattern." (PMID 37845222, 2023). "DT2216 demonstrated superior potency against various BCL-xL-dependent leukemia and cancer cells but considerably less toxicity to platelets than ABT263 in vitro due to the lack of significant VHL expression in platelets." (PMID 36499765, 2022). "The abnormality of the VHL gene can lead to the reduction and accumulation of hypoxia-inducible factor (HIF), thereby initiating the transcriptional activation of hypoxia-responsive genes, and ultimately promoting the occurrence and development of cancer." (PMID 35245343, 2022).
cancer (continued). "However, cancer cells can rapidly develop resistance to new drugs, and preclinical studies using CRBN- or VHL-based PROTACs have revealed that this concern arrives in the real world." (PMID 36140200, 2022). "Furthermore, to induce cancer proliferation, migration, invasion, and apoptosis inhibition, mircoRNA-21 directly targets GAS-5 and VHL pathways." (PMID 35895593, 2022). "If the BRAF gene status did not match in the cancers and metastases, an increase in the level of mTOR mRNA, NFkBp65; VHL; ERα was observed in 32.8; 67.3; 56.0; 1.5 times." (PMID 34319022, 2021). "These VHL–monobody fusions selectively and efficiently degraded KRAS(G12C) in RASless MEFs, as well as endogenous RAS in PATU8902 and H23 cancer cell lines." (PMID 33976200, 2021). "Type 2 VHL is further subdivided into three subtypes depending on the appearance of other cancers: type 2A, PCCs but no ccRCCs, type 2B, PCCs and ccRCCs, or type 2C, PCCs only." (PMID 33151962, 2020). "Moreover, miR-155 creates a signaling pathway with VHL/HIF/VEGF and regulates angiogenesis and the aggressive malignant phenotype of cancer cells." (PMID 33321819, 2020). "Previous studies have clarified that miR‐101‐3p regulates various pivotal oncogenes and that downregulation of this miRNA affects cancer cell proliferation, metastasis, drug resistance, and angiogenesis via targeting of several oncogenic targets, e.g. EZH2, STMN1, VHL, SOX2, and DNMT3A." (PMID 31755218, 2020). "Conversely, data from those two studies suggest that there may be positive feedback between VHL and NEK1 and a potential pathway for cancer and ciliopathy research." (PMID 32294979, 2020). "The VHL protein drives ubiquitination and finally degradation of the hypoxia-inducible factor alpha (HIF) which in turn regulates a number of intracellular pathways that collectively confer resistance to hypoxia to cancer cells." (PMID 32788634, 2020). "Responsiveness of RCCs such as VHL-positive Caki-2 cells for conventional anticancer agents such as camptothecin (CPT), etoposide (VP-16) and doxorubicin (DOX) was lower than that of other types of cancer such as Hela cells." (PMID 30815591, 2019). "ROS can cause DNA damage, the major force driving the transformation of normal cells to cancer cells; however, the role of ROS in TSC or VHL LOH during the development of RCC is unknown and of great interests for the future research." (PMID 29491408, 2018). "Our data suggest that ascorbate intervention is unlikely to prove beneficial in VHL-defective cancer types such as ccRCC." (PMID 30555801, 2018). "This review will focus on VHL-mediated signaling pathways involving the latest identified substrates/binding partners, including N-Myc downstream-regulated gene 3 (NDRG3), AKT, and G9a, etc., and their physiological roles in hypoxia signaling and cancer." (PMID 29562667, 2018). "We found that according to the KEGG enrichment of the common DEGs deregulated upon SOX2OT inhibition; the pathways related to cancer (Kegg: 05200) is one of the most significant enriched pathway (p-value = 0.009285) with 6 genes (HIF1A, HRAS, CHUK, PIK3CA, CDK2, VHL)." (PMID 30202240, 2018). "Staining patterns of pVHL were compared between LOH-positive and -negative cancers for the VHL gene." (PMID 28549422, 2017). "Still, the loss of VHL and increase in HIF transcriptional activity is not sufficient to cause or drive cancer, indicating that additional factors are required for promoting oncogenesis, including the mutation of epigenetic regulators such as PBRM1." (PMID 27100670, 2016). "In this context, downregulation or decreased function of WSB1 would be expected in cancer cells, however, participation of WSB1 in ubiquitin-mediated degradation of a tumor suppressor gene such as VHL may also demonstrate a role for WSB1 as an oncoprotein." (PMID 27542736, 2016).
cancer (continued). "Identified genes included well-known TSGs VHL, CTDSPL, LRRC3B, ALDH1L1, and EPHB1, but also genes not previously linked to cancer development (LRRN1, GORASP1, FGD5, and PLCL2)." (PMID 28326264, 2015). "After splitting up the tumors according to genotype cluster (i.e. cluster 1: SDHx- and VHL-related PCC/PGL; cluster 2: RET-, NF1-, and TMEM127-related tumors), malignant tumors (n = 24) clustered more often in genotype cluster 1 (P<0.0001), compared to benign tumors (n = 33)." (PMID 25794004, 2015). "In contrast, other studies have reported that cases without VHL alterations had better cancer-free and overall survival, with the exception of Stage IV disease, as found in one study." (PMID 22022277, 2011). "Thus, our previous findings showed that zinc supplementation to cancer cells downregulates HIF1α/2α protein levels with a mechanism that involves PHD and VHL, leading to inhibition of HIF-1 activity." (PMID 22202117, 2011). "Even though, surgical management may successfully address VHL-related RCC—as the most frequent type of malignant tumor in VHL—it does not prevent new tumors from forming in the remaining, or contralateral, kidney." (PMID 40796357, 2025). "Finally, our biological studies demonstrate that chemically-induced, VHL-based IRE1 degradation enables effective growth disruption of cancer cell lines that require IRE1 either enzymatically or nonenzymatically, while sparing IRE1-independent cells." (PMID 41381506, 2025). "VHL haploinsufficiency, or “first hit”, is not sufficient to generate cancer; however, it shifts the metabolism by activating some of the Warburg effect factors and some of the mediators of the glutamine reductive metabolism, specifically placing the cells on the path to transformation." (PMID 40362206, 2025). "Furthermore, we demonstrate that VHL-based degradation of IRE1 selectively blocks growth of IRE1-dependent cancer cell lines regardless of their mode of dependency on IRE1, while sparing IRE1-independent cells." (PMID 41381506, 2025). "The true-positive rate of 64% emphasizes the patients who derive the most benefit from WB-MRI screening—those patients with LFS, MEN1, and VHL, whose cancers were found at an early, nonmetastatic stage and were treated with curative intent via surgery and systemic therapy." (PMID 40138602, 2025). "Although the relationship between VHL and YAP1 in RCC progression is not clear, YAP1 could be associated with HIF-1α (a major downstream target of VHL) in cancer cells under hypoxic conditions to induce VEGF-A transcription." (PMID 39123485, 2024). "We report AU-15330 as a novel, highly specific and VHL-dependent PROTAC degrader of SWI/SNF ATPase components (SMARCA2, SMARCA4 and PBRM1) that shows preferential cytotoxicity in enhancer-binding transcription factor-addicted cancers at low nanomolar concentrations." (PMID 34937944, 2022). "The choice of an E3 ligase that is preferentially expressed in cancer cells, such as VHL, conjugated to a senolytic moiety, may confer greater selectivity for senescent cancer cells over senescent, non-malignant cells." (PMID 33578753, 2021). "Cancer cells develop mechanisms that increase nutrient uptake, including key nutrient carriers, such as amino acid transporter 1 (LAT-1) and glucose transporter 1 (GLUT-1), regulated by the oxygen-sensing Von Hippel Lindau-hypoxia-inducible factor (VHL-HIF) transcriptional pathway." (PMID 33066332, 2020). "Taken together, these results demonstrated that p19-VHL was expressed in all cancer cell lines tested, whereas none of the tested cell lines expressed p30-VHL, and that p19-VHL was expressed in different oligomeric states, including monomers, dimers, trimers, tetramers, and HMW VHL." (PMID 28580172, 2017). "Besides VHL and SETD2, the compound was also selective for cancer cells with mutation in PTEN and CDKN2A (data not shown)." (PMID 25853938, 2015).
cancer (continued). "Interestingly, a higher PLA2R1 mRNA level was found in VHL functional ACHN cells than in any of the VHL nonfunctional cancer cell lines." (PMID 24657971, 2014). "Thus, H3K36me3 deregulation drives oncogenesis and metastasis in cancers beyond RCC, suggesting that SETD2's tumor/metastasis suppressor function is conserved among different tissues and independent of mutations commonly linked to ccRCC like VHL and PBRM1." (PMID 37418588, 2024). "Contrary to the result obtained from the VHL-positive Caki-2 cells, 15d-PGJ2 did not enhanced the anti-cancer activity of topoisomerase inhibitors synergistically in the VHL-positive RCC4(+) cells." (PMID 30815591, 2019). "Contrary to the result obtained from the VHL-positive Caki-2 cells, 15d-PGJ2 did not enhanced the anti-cancer activity of topoisomerase inhibitors synergistically in the VHL-positive ACHN cells." (PMID 30815591, 2019). "The reason why organ specific VHL-related lesions respond differently to anti-angiogenic therapy is unclear, though RCC and HBs are inherently different as HBs do not represent true cancer and lack metastatic potential." (PMID 29805741, 2018). "We studied VHL and VEGF levels in macrophages incubated with culture supernatant of hypoxia primed cancer cells and not in hypoxic cancer cells themselves." (PMID 25051364, 2014). "Recently, novel BCL-XL proteolysis targeting chimeras (PROTACs) have been developed to degrade BCL-XL in cancer cells but not platelets, as it targets BCL-XL to the VHL E3 ligase for ubiquitination and proteasomal degradation and platelets express very low levels of VHL." (PMID 41507122, 2026). "In addition, a VHL-based proteolysis-targeting chimera (PROTAC) degrader of BRG1, called AU-1533015, was used to treat two non-ccRCC cancer cell lines that express VHL (A375 MA2, HCT116) as well as a normal renal epithelial cell line (HK-2)." (PMID 40473600, 2025). "In addition, VHL has other targets that are independent of HIF‐1 in C. elegans, mice and cancer cells." (PMID 38320757, 2024). "Taken together, the data presented here show that YAP1 can be regulated by a novel nonclassical pathway under normoxic conditions, which involves PHD2 and VHL; absence of this regulation under hypoxic conditions stabilizes YAP1 protein and contributes to angiogenesis and cancer progression." (PMID 35937460, 2022). "However, expression of VHL was not regulated by SCG2 in cancer cells, suggesting that SCG2 may promote the role of HIF‐1α in ubiquity degradation via binding VHL." (PMID 34160138, 2021). "To ascertain whether VHL was involved in the synergy between topoisomerase inhibitors and 15d-PGJ2, we compared the synergism of anti-cancer agents with 15d-PGJ2, in VHL-positive cell lines (Caki-2, ACHN and RCC4 (+)) and VHL-negative cell lines (786-O cells and RCC4(-))." (PMID 30815591, 2019).
infection (22 papers, 2013 to 2025). The state of being infected such as from the introduction of a foreign agent such as serum, vaccine, antigenic substance or organism. "Compared with WT cells or cells infected with VHL, aNSa1 and VHL-aNSa1, infection of cells with aCS3 and VHL-aCS3 caused a reduction in BCR-Abl-induced total phospho-Tyr levels." (PMID 28490657, 2017). "In contrast to previous observation that VHL deficiency enhances effector responses of T cells, mice with VHL-loss in T cells (Vhl cKO) showed a dramatically increased susceptibility to infection with M. tuberculosis by failing to accumulate M. tuberculosis-specific CD4 and CD8 T cells in the lungs." (PMID 36064840, 2022). "A series of indomethacin-based PROTACs has recently been reported that target SARS-CoV-2 main protease to VHL, and inhibit infection in human lung cells." (PMID 39929804, 2025). "Consistent with increased Vpx stability, SAMHD1 was degraded more efficiently in VHL-knockdown cells following infection with wild-type HIV-2-Luc compared to control cells." (PMID 40522994, 2025). "Immunization with TB40/E and VHL/E produced antibodies capable of effectively neutralizing AD169R infection in epithelial cells with >90% neutralization at a 1:500 dilution in 3/5 mice." (PMID 35468974, 2022). "The mRNA level of VHL was increased by hypoxia, which was augmented by LPS and by infection with wild-type or ΔdotA C. burnetii." (PMID 35755850, 2022). "Using conditional knockouts in T lymphocytes and mouse models of infection, VHL was determined to negatively regulate a HIF-mediated shift toward glycolytic metabolism — a key metabolic event for the initiation of Tfh cell development." (PMID 33830079, 2021). "The results showed that infection of Ad-VHL inhibited intracellular αSMA expression and HSC activation." (PMID 28112200, 2017). "First trimester placenta blocks were obtained from 12 donors and cultured 5 days at the air-liquid interface in the presence of VHL/E-HCMV-producing MRC5 fibroblasts to allow efficient infection." (PMID 26171612, 2015). "Transient cotransfection of human U87 and LN229 cells with lenti-AS-566 and a wild-type VHL 3’ UTR plasmid led to a significant increase in luciferase reporter activity compared to infection with lenti-NC." (PMID 24650032, 2014). "A more important finding was that Ad-VHL injection upregulated the expression of VHL in HSCs in vivo, and along with enhanced intracellular VHL expression, intracellular αSMA expression and HSC activation were inhibited by Ad-VHL infection compared with Ad-Null." (PMID 28112200, 2017). "Thus, we knocked down the remaining VHL mRNA by infection with lentivirus-expressing VHL shRNA." (PMID 27682873, 2017). "Before proceeding with further P. berghei UIS4-HT infection experiments, validation assays were conducted to assess the activity of a VHL control binder (without the HaloTag ligand portion) and HaloPROTAC320 in relevant host cells." (PMID 40419780, 2025). "We studied the role of VHL and HIF-1 in T cells in the outcome of infection with 250 M." (PMID 36064840, 2022). "Infection of cells with any of aCS3, VHL-aCS3, aNSa1 and VHL-aNSa1 did not result in changes in HIF1α protein levels, suggesting that the expression of the AdPROM system does not interfere with hypoxia signalling." (PMID 28490657, 2017). "The infection of cells with aNSa1, VHL-aNSa1, aCS3 and VHL-aCS3 did not alter the levels of phospho-STAT3-Tyr705 or phospho-STAT5-Tyr694." (PMID 28490657, 2017). "Recent reports have revealed a crucial role for VHL and HIF in regulating the function of Tfh cells to promote (i) B cell differentiation into antibody-producing plasma cells and memory B cells following infection and immunization, and (ii) the production of high-affinity antibodies." (PMID 33830079, 2021). "We have used the RCC4 VHL cell line as a control to verify whether the ability of infection by LCMV is independent of the VHL status." (PMID 29560117, 2018).
infection (continued). "With these results, we have thus proven that the RCC4 and RCC4 VHL cell lines could be infected by the MX strain of LCMV, and this infection is not affected by the VHL mutation." (PMID 29560117, 2018).
metabolic disease (10 papers, 2009 to 2026). A congenital disorder (due to inherited enzyme abnormality) or acquired (due to failure of a metabolically important organ) disorder resulting from an abnormal metabolic process. "As a metabolic disease, many mutated genes, such as VHL, fumarate hydratase (FH), and succinate dehydrogenase (SDH), are involved in cellular respiration and energy metabolism." (PMID 32461965, 2020). "Due to the alteration of the von Hippel-Lindau (VHL) gene and activation of the Ras-PI3K-AKT-mTOR pathway, the RCC is occasionally considered as a “Metabolic Disease”; besides, the reprogramming of the fatty acid metabolism is one of the most associated pathways." (PMID 35222406, 2022). "However, the interplay between VHL/HIF-mediated pseudohypoxia and metabolic disorder in PPGLs cells is not well-defined." (PMID 33329393, 2020).